MMP9 (matrix metallopeptidase 9)
Diseases named in the same sentence as MMP9 in open-access papers (continued):
Sharing a sentence is not in itself a finding about the gene and the disease.
cervical carcinoma (continued). "The high expression and activity of MMP-2 and MMP-9 have been recognized to be correlated with HPV presence in cervical cancer and the present results were obtained in HPV positive cervical cancer cells." (PMID 30484490, 2018). "b The expression of MMP-2 and MMP-9 increase in all groups of cobalt chloride (150 μM) treated cervical cancer cells." (PMID 28507454, 2017). "Inhibiting MMP-9 activity in SiHa and HeLa cervical cancer cells reduced their migratory and invasive ability." (PMID 28427184, 2017). "Previous studies demonstrated that the expression of MMP-2 and MMP-9 is crucial in cervical cancer metastasis." (PMID 29088748, 2017). "The depletion of PTX3 inhibited EGF-induced MMP-9, which was consistent with the association between MMP-9 and PTX3 expression observed in cervical cancer cell metastasis." (PMID 28489600, 2017). "MMP-2 and MMP-9 have important roles in the development of malignant cervical cancer in animal models and humans." (PMID 29267213, 2017). "Our findings suggest that HOXA11-AS promotes cervical cancer cell migration and invasion via upregulation of MMP-9, MMP-2, and VEGF." (PMID 27792998, 2016). "Based on these results, Bufalin appeared to halt cervical cancer cell invasion and migration possibly by simulating the expression of MMP9 and Snail1 and suppressing the expression of E-cadherin." (PMID 26758421, 2016). "The conclusion of the study was that resveratrol inhibits NF-κB and AP-1 transactivation suppressing the transcription of MMP-9, leading to suppression of migration and invasion of cervical cancer cells." (PMID 27548122, 2016). "A study conducted on CaSki cervical cancer cells showed a decreased expression of MMP-9 after exposure to resveratrol." (PMID 27548122, 2016). "Gelatinase B/MMP-9 degrades the IL-2 receptor α, repressing activation and proliferation of tumour infiltrating T-lymphocytes in cervical cancer." (PMID 24473089, 2014). "After treating with IL-17A, the expression of MMP2 and MMP9 proteins in cervical cancer cell lines (C33A and Caski) was increased, meanwhile the expression of TIMP-1 and TIMP-2 proteins was decreased." (PMID 25250801, 2014). "Zoledronic acid has been shown to inhibit macrophage gelatinase B/MMP-9 and reduces angiogenesis in a model of papillomavirus-induced cervical cancer." (PMID 24473089, 2014). "Using a murine model of cervical cancer, Pahler and co-workers showed that macrophages and neutrophils infiltrating the tumor are the source of the MMP-9 secreted into the tumor stroma." (PMID 22438955, 2012). "Increased mRNA and protein levels of both MMP-2 and MMP-9 have been detected in breast, colon, pancreatic and cervical cancers." (PMID 15989693, 2005). "The lymphangiogenic factor VEGF-C and MMP-9 were upregulated 130- and 80-fold respectively in cervical cancers." (PMID 12189553, 2002). "Another investigation showed that FA (4 μM) could suppress migration of Hela and CaSki cervical carcinoma cell lines by increasing the cell cycle arrest in the G0/G1 phase and decreasing MMP9, mRNA expression, and cyclin D1 and cyclin E levels." (PMID 40487371, 2025). "Additional examination revealed that bergenin is a powerful anti-angiogenic substance, as it decreased the levels of essential angiogenic proteins, such as Galectin 3 and MMP-9, in cervical cancer cells at the cellular level, as demonstrated by a western blotting assay." (PMID 39834829, 2024). "Cumulatively, our data provide novel insight into the anti-angiogenic mechanism of bergenin in cervical carcinoma cells by modulation of multiple angiogenic proteins like Galectin-3 and MMP-9 which warrant its further development as an anticancer agent in cervical cancer." (PMID 38961106, 2024). "However, we fully recognize the significance of MMP-2 and MMP-9 in cervical cancer progression and plan to explore their activity in future investigations." (PMID 38617545, 2024).
cervical carcinoma (continued). "Although the presence of Th17 cells in situ was linked with cervical cancer progression, and IL‐17A was found to upregulate MMP‐2 and MMP‐9 expression favoring migration of cervical cancer cell lines, Th17‐induced mechanisms underlying cervical cancer metastases are not reported so far." (PMID 37899663, 2024). "Similarly, we also discovered that Oct4 promoted p38 phosphorylation level and MMP2 and MMP9 levels in cervical cancer cells, indicating the activation of the p38 pathway." (PMID 38430256, 2024). "In addition, we investigated the protein levels of vimentin, S100A4, αSMA, FAP, MMP9, and Ki67 in different stages of cervical cancer." (PMID 38606999, 2024). "Bortezomib treatment reduces the migration and invasive capacity of a cervical carcinoma HeLa cell line, which was associated with a decrease in the intracellular expression of MMP2 and MMP9, and this is also observed in bortezomib treated chondrosarcoma cells." (PMID 36302993, 2023). "Furthermore, genistein inhibited cervical cancer cell migration, an effect that was correlated with enhanced MMP-9 protein levels." (PMID 38201463, 2023). "It stimulates the expression of MMP-2 and MMP-9 in endometrial and cervical cancers." (PMID 36982551, 2023). "Post-radiation increase of MMP-9 expression in cervical cancer is associated with increased ADC values, indicating that ADC can be used as a biomarker for predicting tumor response assessment of cervical cancer." (PMID 36139628, 2022). "Relevant research showed, trametinib combined with PI3K/mTOR dual inhibitor dactylitis can eliminate the enhancement of nuclear receptor related-1 protein (Nurr1) to cervical cancer cell aggressiveness by upregulating p21 and p27 expression and inhibiting MMP9 and KLF4 expression." (PMID 36204323, 2022). "We revealed that TUSC3 may modulate the AKT and regulate MMP9 to enhance cervical cancer cells invasion." (PMID 35137520, 2022). "The results indicated that MMP-9 promotes bladder and cervical cancer invasion and metastasis." (PMID 35178444, 2022). "To generalize our findings, we studied the impact of MMP‐9 on MICA/B in the Hela cervical cancer that is known to express high levels of MICA/B. Similarly, MMP‐9 also decreased cell surface expression levels of MICA/B in Hela cells and SB‐3CT counteracted the MMP‐9 effect." (PMID 34486239, 2021). "MMP-2 and MMP-9 are involved in metastasis due to their ability to degrade collagen type IV of the basement membrane of blood vessels, and their overexpression is related to the progression of cervical carcinoma." (PMID 32455616, 2020). "Moreover, PRDX1 overexpression increased invasion and migration of SiHa cervical cancer cells via up-regulating the expression of Snail and matrix metalloprotein 9 (MMP-9) and down-regulating the expression of E-cadherin." (PMID 31956363, 2020). "This study aimed to assess whether the expression of MMP-2, MMP-9, MMP-14, TIMP-1, and TIMP-2 in tumors and in the adjacent stroma is associated with cervical cancer prognosis." (PMID 32669083, 2020). "Previously, it was found that stimulation of cervical carcinoma A431 cells by recombinant MMP-9 led to an acquisition of spindle-like phenotype by the cells; furthermore, knockdown of MMP-9 by siRNA significantly reduced expression of mesenchymal markers vimentin and fibronectin in these cells." (PMID 33327637, 2020). "Investigations into cervical cancer cells demonstrated that the overexpression of miR‐204 could reduce the expression of MMP‐9 through the activation of the PI3K/AKT signalling pathway." (PMID 31389660, 2019). "Additionally, the secretion of MMP-2 and MMP-9 was demonstrated to be involved in the proteolytic events required for tumor migration and metastasis in human cervical cancer." (PMID 31572058, 2019).
cervical carcinoma (continued). "Higher levels of MMP-9 have been discovered in various types of cancer, which has led to its potential role as a biomarker in giant-cell tumor of the bone, non-small cell lung cancer and cervical cancer, among others." (PMID 31687607, 2019). "Furthermore, CREB3 plays a significant role in cervical cancer progression via the c-Jun-mmp9 axis and is involved in the malignant phenotype of prostate cancer." (PMID 30940151, 2019). "Finally, patients with early stages of cervical cancer showed higher MMP-9 expression and experienced a decreased recurrence-free survival after standard treatment." (PMID 30208169, 2018). "Noteworthy, in this previous study, 30 μM cisplatin caused no significant alterations in MMP-9 or TIMP-2 expression in cervical carcinoma cells or in TIMP-2 expression in A549 cells." (PMID 30344920, 2018). "Patients with cervical cancer of positive MMP-9 staining tend to have worse overall survival." (PMID 30262739, 2018). "MMP-9 expression was found to be elevated in cervical cancer." (PMID 30262739, 2018). "Therefore, FA inhibited the cell invasion in Hela and Caski cervical cancer cells through reducing the expression of MMP-9." (PMID 30013454, 2018). "Furthermore, we found that GPNMB accelerated the tumorigenesis of cervical cancer in vitro by regulating MMP-2/MMP-9 activity via the Wnt/β-catenin pathway." (PMID 30484490, 2018). "It would be very interesting to clarify whether there are possible associations among GPNMB, MMP-2/MMP-9, and HPV oncogenes, and whether GPNMB plays a role in HPV-negative cervical cancer cells in future study (26, –28)." (PMID 30484490, 2018). "This study indicates that MMP-9 expression in cervical cancer is an independent prognostic factor." (PMID 30262739, 2018). "Even though MMP proteolytic network alterations are common during the progression of cervical cancer, only upregulation of the expression/activity of MMP-2 (gelatinase A) and/or MMP-9 (gelatinase B) seems to be indicative of a poor prognosis in cervical cancer patients 22,57,58." (PMID 30208169, 2018). "Thus, cervical cancer-derived IL-6 immobilizes dendritic cells in the tumor stroma via CCR7 suppression facilitating local MMP-9 production." (PMID 28895886, 2017). "In addition, the high expression level of HOTAIR in cervical cancer tissues associated with upregulation of VEGF and MMP-9 expression levels compared with the low expression groups." (PMID 25405331, 2015). "Furthermore, the activity of MMP2 and MMP9 secreted by cervical cancer cells was examined by zymography assay." (PMID 25250801, 2014). "Importantly, high MMP-9 expression levels and activity have been correlated with poor clinical outcome in cervical cancer patients." (PMID 22438955, 2012). "However, the results obtained from this study suggest that PVT1 could be involved in MMP2 and MMP9 regulation by ALKBH5 in cervical cancer cells." (PMID 37639643, 2023). "Furthermore, Western blot analysis was used to detect the expression of N‐cadherin, vimentin, MMP‐2 and MMP‐9 in cervical cancer cells, the results of which showed an up‐regulation in these proteins upon E2F4 silencing or C16orf74 overexpression in the presence of HAND2‐AS1 overexpression (P < .05)." (PMID 32314545, 2020). "Additionally, MMP-2 and MMP-9 expression could also be regulated by histone deacetylases (HDACs), a key enzyme of epigenetic regulation, to affect cervical cancer metastasis." (PMID 30484490, 2018). "Therefore, we wonder whether heterologous expression of NaV1.6 channels in cervical cancer cells induces secretion of the gelatinases associated to cell invasion, i.e., MMP-2 and MMP-9." (PMID 30158710, 2018). "Notably, both CCR7 and MMP-9 up-regulation are mediated by IL-6 from the cervical cancer cells." (PMID 28895886, 2017).
cervical carcinoma (continued). "In addition, western blot analysis revealed that the pre-treatment of SB203580 and PDTC abrogated the upregulation of MMP2 and MMP9 induced by IL-17A, further demonstrating that IL-17A regulated MMPs expression and invasion of cervical cancer cells via activating p38/NF-κB signal pathway." (PMID 25250801, 2014). "However, an approximately 80-fold increase was observed for MMP-9 mRNA in cervical cancers." (PMID 12189553, 2002). "However, an approximately 80-fold increase in MMP-9 mRNA was observed in cervical cancers." (PMID 12189553, 2002). "Upregulation of TIMP-1 forms the MMP-9 and MMP-2, which are inhibitory complexes that initiate anti-invasion of cervical cancer." (PMID 40008130, 2025). "This study aimed to evaluate the protein expression of vimentin, S100A4, αSMA, FAP, and MMP9 in mesenchymal stem cells (MSC)-CAF cells, as well as in cervical cancer samples." (PMID 38606999, 2024). "While measuring MMP-2 and MMP-9 activities would undoubtedly provide valuable insights, our current investigation focuses on understanding TIE1's broader impact on the cervical cancer progression." (PMID 38617545, 2024). "For these reasons, this study evaluated the effect of supernatants from cervical cancer cell lines (HeLa and SiHa) in the expression of vimentin, S100A4, αSMA, FAP, and MMP9 markers in an in vitro MSC-CAF model." (PMID 38606999, 2024). "Resveratrol (20 μM, 40 μM) also suppressed the migratory and invasive abilities of cervical cancer cells by reducing MMP-2 and MMP-9 protein expression." (PMID 39335164, 2024). "In advanced stages of cervical cancer, we found that there is an overexpression of FAP and MMP9 with a positive trend." (PMID 38606999, 2024). "Studies have demonstrated that knockdown of FTS (Fused Toes Homolog), an oncogene involved in cervical cancer pathogenesis, suppresses cell migration by downregulating MMP-2 and MMP-9 in cervical cancer." (PMID 37986152, 2023). "Piperine has been shown to regulate MMP2, MMP9, TIMP1, and TIMP2 in cervical cancer cells at the gene and protein levels." (PMID 36678600, 2023). "SiHa and HeLa human cervical cancer cell migration can be blocked by ALA (10–80 μM) by the downregulation of VEGF, MMP-2, and MMP-9 expression." (PMID 38068849, 2023). "Higher concentrations of MMP9 and a lower concentration of TIMP2 were found in patients with cervical cancer and CIN3, compared to patients with ectropion." (PMID 36982551, 2023). "FN1 upregulation has been reported to activate MMP2 and MMP9 via the FAK and PI3K/Akt pathways, promoting tumor metastasis in lung, gastric, breast, ovarian and cervical cancer." (PMID 36151071, 2022). "MMP-9 levels have been proposed as a biological predictor of prognosis in CRC and other cancers such as breast and cervical cancer." (PMID 36110531, 2022). "For example, inhibition of DPP8 expression in cervical cancer cells can inhibit cell proliferation, migration, and invasion by affecting the expression of Bax and BCL2, inhibiting the expression of MMP2 and MMP9." (PMID 36172198, 2022). "Based on cell and animal experiments, we concluded that KNTC1 can enhance the invasion, migration, and tumorigenicity of tumor cells via MMP2 and MMP9, providing a basis for the subsequent study of KNTC1 as a target for cervical cancer treatment." (PMID 35389773, 2022). "In the mechanism, the extracellular matrix is degraded and the basal membrane expression of cervical cancer cells is destroyed by up-regulating the expression of MMP-2 and MMP-9, thereby resulting in carcinogenesis and metastasis." (PMID 35445019, 2022). "Evidence also suggests that PTX3 promotes metastasis of cervical cancer and EGF-induced metastasis of HNSCC through upregulation of MMP-2 and MMP-9." (PMID 34917682, 2021). "As shown in this study, exogenous expression of HK2 activated Akt1 (p-Akt1) in cervical cancer cells, subsequently enhancing cell motility and tumor metastasis by inducing FN1, MMP2 and MMP9 expression." (PMID 34758823, 2021).
cervical carcinoma (continued). "At the same time, the majority of the studies supported the view that increased MMP-9 can also promote the development of cervical cancer, although a few articles have suggested that MMP-9 was helpful for cervical cancer prognosis." (PMID 34717710, 2021). "Clinical studies identified MMP-9 as a potential prognostic biomarker for various tumor entities such as NSCLC, cervical cancer, pancreatic cancer, and osteosarcoma." (PMID 34055644, 2021). "WB assays showed that the expression levels of MMP-2 and MMP-9 proteins were significantly reduced, indicating that UBE2R2-AS1 inhibits the invasion and the migration of cervical cancer cells by regulating MMP-2/9 expression." (PMID 33336075, 2020). "We also demonstrated that up‐regulation of C16orf74 can rescue the inhibitory role HAND2‐AS1 overexpression has on cervical cancer cell proliferation, migration and invasion, as evidenced by promoted expression of N‐cadherin, vimentin, MMP‐2 and MMP‐9." (PMID 32314545, 2020). "Here, we confirmed that cervical cancer cells upregulated the expression of MMP2, MMP9, and MMP12 of SCs." (PMID 32064233, 2020). "We further validated that the overexpression of miR-128 markedly decreased ITGA5, ITGB5, sLex, CEACAM-6, MMP-9, and MMP-23 in SSR-HeLa and SSR-CaSki cervical cancer cell clones." (PMID 33379338, 2020). "After validation by quantitative RT-PCR, we discovered that diminished miR-128 in WT-HeLa or WT-CaSki cells markedly increased the expression levels of ITGA5, ITGB5, sLex, CEACAM-6, MMP9, and MMP23 in WT-HeLa and WT-CaSki cervical cancer cell clones." (PMID 33379338, 2020). "HOTAIR expression causes the up regulation of the vascular endothelial growth factor (VEGF), matrix metalloproteinase-9 (MMP-9) and EMT-related genes thus promoting tumor aggressiveness in cervical carcinoma." (PMID 32154165, 2020). "Treating cervical cancer cells with an NF-κB inhibitor potently reversed PLA-induced migratory and invasive behavior, MMP-9 upregulation, and/or E6/E7 downregulation." (PMID 31572058, 2019). "In conclusion, we demonstrated that GPNMB contributed to the tumorigenesis of cervical cancer, at least in part, by regulating MMP-2/MMP-9 activity in tumor cells via activation of canonical Wnt/β-catenin signaling." (PMID 30484490, 2018). "MMP-9 level has been suggested as a biological predictor of prognosis in CRC as well as in other types of cancer such as breast and cervical cancer." (PMID 29520667, 2018). "MMP-9 specific activity and/or MMP-2 active protein levels were (I) increased in HSIL and cervical cancers when compared to normal control tissues (II) and correlated with increased lymph node metastasis and cancer relapse 22,63." (PMID 30208169, 2018). "We herein determined that expression and activity of MMP-2 and MMP-9 were aberrantly increased, but were significantly decreased by GPNMB siRNA in cervical cancer cells in vitro." (PMID 30484490, 2018). "Our results showed that inhibition of CCL19 inhibited expression of MMP-9 and MMP-2, suggesting that CCL19 increase the aggressiveness of cervical cancer cells, possibly by regulation of MMP-2 and MMP-9." (PMID 29088748, 2017). "The anti-viral drugs ribavirin and indinavir appear to protect against HPV-18-induced cervical cancer by decreasing the secretion of MMP-2 and MMP-9." (PMID 29267213, 2017). "In our investigation, high expression of HOXA11-AS in cervical cancer cell induced cell migration and invasion through the upregulation of EMT-related genes, VEGF, and MMP-9." (PMID 27792998, 2016). "Taken together, our findings demonstrate that HOTAIR accelerates the aggressiveness of cervical cancer cells through the upregulation of VEGF and MMP-9." (PMID 25405331, 2015). "Although overexpression of several types of MMP has been observed in cervical cancer tissues, only increased levels of MMP-2 and MMP-9 were shown to correlate with poor prognosis in patients." (PMID 23967226, 2013).